SRRM4 (serine/arginine repetitive matrix 4)
Description:
Splicing factor specifically required for neural cell differentiation. Acts in conjunction with nPTB/PTBP2 by binding directly to its regulated target transcripts and promotes neural-specific exon inclusion in many genes that function in neural cell differentiation. Required to promote the inclusion of neural-specific exon 10 in nPTB/PTBP2, leading to increased expression of neural-specific nPTB/PTBP2. Also promotes the inclusion of exon 16 in DAAM1 in neuron extracts (By similarity). Promotes alternative splicing of REST transcripts to produce REST isoform 3 (REST4) with greatly reduced repressive activity, thereby activating expression of REST targets in neural cells. Plays an important role during embryonic development as well as in the proper functioning of the adult nervous system. Regulates alternative splicing events in genes with important neuronal functions (By similarity).
Synonyms: nSR100; KIAA1853; MU-MB-2.76
Tractability: PROTAC: ubiquitination databases record sites on it.
Gene: Protein-coding gene on chromosome 12 (118,981,541 to 119,163,051, forward strand). Ensembl gene ENSG00000139767.
Subcellular location: Nucleus
Gene Ontology:
Molecular function: identical protein binding; protein binding; mRNA binding
Biological process: regulation of alternative mRNA splicing, via spliceosome; cell differentiation; mRNA processing; nervous system development; neuron maturation; regulation of RNA splicing
Cellular component: nucleus
Genetic constraint (gnomAD): Loss-of-function variants: 30 observed, 62.23 expected, observed/expected ratio (o/e) 0.48, 90% interval 0.36 to 0.65. The upper end of that interval is the gene's LOEUF score, 0.65, which puts it in group 2 of 6, group 1 being the genes least tolerant of losing a copy. Missense variants: 797 observed, 800.84 expected, observed/expected ratio (o/e) 1, 90% interval 0.94 to 1.05. Synonymous variants: 312 observed, 306.71 expected, observed/expected ratio (o/e) 1.02, 90% interval 0.93 to 1.12.
Homologues: Orthologues: chimpanzee SRRM4 (99% identical), macaque SRRM4 (98% identical), guinea pig SRRM4 (90% identical), pig SRRM4 (89% identical), rabbit SRRM4 (87% identical), mouse Srrm4 (84% identical), dog SRRM4 (83% identical), rat Srrm4 (78% identical), tropical clawed frog srrm4 (52% identical).
Diseases named in the same sentence as SRRM4 in open-access papers:
SRRM4 is named in the same sentence as 41 diseases in open-access papers, as found by Europe PMC text mining. Sharing a sentence is not in itself a finding about the gene and the disease. The quoted sentences say what the papers report.
prostate carcinoma (7 papers, 2017 to 2026). A carcinoma that arises from epithelial cells of the prostate gland. "Further, effectiveness of SRRM4 ASO to prostate cancer (PCa) cells expressing SRRM4 similar to SCLC remains to be elucidated." (PMID 36650528, 2023). "SRRM4 up-regulation drives splicing switches towards neuronal splicing patterns and the trans-differentiation of prostate cells towards neuroendocrine prostate cancer cells." (PMID 28382513, 2017). "In fact, it has been suggested that SRRM4 mediates increased SOX2 expression, driving prostate cancer cells to a pluripotent phenotype and favoring tumor growth." (PMID 33621242, 2021). "Overexpression of NK1R in epithelial prostate cancer cells was able to induce a shift of lineage plasticity, leading to the reduction of AR and PSA levels, the gain of the expression of CgA, ENO2, AURKA, N-Myc, MYT1, and SRRM4." (PMID 37385990, 2023). "Spliced by SRRM4, the MEAF6-1 variant does not mediate neuroendocrine differentiation of prostate cancer cells, but rather promotes cell proliferation and invasion to accelerate tumor growth." (PMID 28427194, 2017). "While we show that SRRM4 overexpression inhibits cell proliferation in all cancer cell lines tested (including the prostate cancer cell line DU145), in our experiments, SRRM4 did not induce SOX2 expression, which could explain the apparent contradiction." (PMID 33621242, 2021). "Important SRRM4-regulated events include a splicing switch in the transcription factor REST1 (RE1 silencing transcription factor) which is a master regulator of neurogenesis, thus providing a possible molecular explanation for the neuroendocrine prostate cancer phenotype." (PMID 28382513, 2017).
autism (6 papers, 2017 to 2024). Persistent deficits in social interaction and communication and interaction as well as a markedly restricted repertoire of activity and interest as well as repetitive patterns of behavior. "One of these compounds rescues the splicing of several analyzed microexons in the cerebral cortex of an autism mouse model haploinsufficient for Srrm4, a major activator of brain microexons." (PMID 39068192, 2024). "Importantly, they postulated that nSR100.SRRM4 could potentially be a target for diagnostics and therapeutic intervention in autism." (PMID 33102526, 2020). "Furthermore, the change in Srrm4 expression and microexon inclusion may have functional consequences that contribute to ASD pathogenesis and suggest a potential shared pathophysiology between the Pten and Srrm4 model of autism." (PMID 33159038, 2020).
autism spectrum disorder (6 papers, 2017 to 2025). A spectrum of developmental disorders that includes autism, and Asperger syndrome. "There have been reports on the development of antisense nucleic acid drugs targeting SRRM4 for the treatment of small-cell lung cancer and its association with autism spectrum disorder, and it has been suggested that silencing of SRRM4 in tumors may favor growth." (PMID 41463596, 2025). "In the case of microexons, SRRM4 and RBFOX1 have a critical role in coordinating microexon inclusion through brain development, and changes in the expression of these splicing factors have been linked to misregulation of alternative splicing events in individuals with autism spectrum disorder (ASD)." (PMID 33482885, 2021). "Notably, neurons from individuals with autism spectrum disorder exhibited mis-regulated splicing of the microexon network and a corresponding reduction in SRRM4/nSR100 expression." (PMID 40207498, 2025).
deafness (4 papers, 2012 to 2024). An inherited or acquired condition characterized by the complete loss of the ability to hear from one or both ears. "For instance, a mutation in Srrm4 in mice leads to defective AS in hair cells and deafness, while AS profiles are preserved in the brain, partly due to the developmental upregulation of Srrm3." (PMID 38438733, 2024). "Loss of SRRM4 function due to a deletion mutation in the Bronx waltzer mouse line (Srrm4bv/bv) is associated with balance defects, deafness, and perinatal degeneration of nearly all VHCs as well as ∼75% of inner HCs (IHCs)." (PMID 33087486, 2020). "Rest is one of many pre-mRNAs whose alternative splicing is regulated by the splicing factor SRRM4; Srrm4 loss-of-function mutation in mice (Srrm4bv/bv) causes deafness, balance defects, and degeneration of all HC types other than the outer HCs (OHCs)." (PMID 33087486, 2020). "Another study showed that an inactivating mutation in the SRRM4 gene caused deafness and balance impairments in Bronx Waltzer mice." (PMID 29666783, 2018). "In this study, we localize the deafness-causing gene defect of the bv mouse line to the splicing factor-encoding gene Srrm4 (also known as nSR100)." (PMID 23055939, 2012). "In these mice, the deletion impaired the splicing activity of SRRM4, but resulted in limited abnormal neural behaviors, such as deafness and impaired balance." (PMID 29666783, 2018).
small cell lung carcinoma (4 papers, 2019 to 2025). Small cell lung cancer (SCLC) is a highly aggressive malignant neoplasm, accounting for 10-15% of lung cancer cases, characterized byrapid growth, and early metastasis. "A series of recent studies have suggested that SRRM4 may play a role in the progression of small-cell lung cancer and NE prostate cancer by inactivating the RE1-silencing transcription factor (REST), in turn promoting expression of neuronal genes." (PMID 33621242, 2021).
Anxiety (2 papers, 2024 to 2025). Intense feelings of nervousness, tension, or panic often arise in response to interpersonal stresses. "However, it is unclear how the bv-causing Srrm4 mutation affects GABAergic interneurons to cause anxiety." (PMID 38229888, 2024). "Therefore, different Srrm4 genotypes appear to show variable phenotypic expressions, and only bv/bv mice could serve as a model for anxiety associated with Srrm4." (PMID 38229888, 2024). "Thus, our initial hypothesis that Srrm4 is expressed in GABAergic interneurons was unsupported; instead, the bv-associated Srrm4 mutation may cause anxiety by altering gene expression in glutamatergic neurons rather than in GABAergic interneurons." (PMID 38229888, 2024). "However, the cellular consequences of the Srrm4 mutation for anxiety remain unknown." (PMID 38229888, 2024). "Because Srrm4 regulates alternative splicing of neuronal transcripts, these findings suggest that proper splicing prevents mice from showing anxiety, and that bv/bv mice could be used as a model to study the effect of alternative splicing in anxiety disorders." (PMID 38229888, 2024). "Clarifying these genes may further delineate the molecular mechanisms by which Srrm4 contributes to anxiety in bv/bv mice." (PMID 38229888, 2024). "Our study showed that Srrm4 is not expressed in GABAergic interneurons, which appear to be intact in bv/bv mice when they show anxiety phenotype." (PMID 38229888, 2024).
lung carcinoma (2 papers, 2019 to 2023). "We found that our gASO repressed SRRM4 synthesis leading to a dramatic tumor reduction in a lung cancer mouse model." (PMID 31110284, 2019). "For example, SRRM4 and NAV3 are reported to regulate lung cancer and colorectal cancer, respectively." (PMID 37604131, 2023).
neuroendocrine tumor (2 papers, 2019 to 2023). "Alternative splicing of REST from sREST to REST might be a potential cause of anti-tumor effects by SRRM4 ASO in neuroendocrine tumors SCLC as well as PCa." (PMID 36650528, 2023). "Thus, SRRM4 was selected as a therapeutic target for the neuroendocrine tumor SCLC as well as PCa." (PMID 36650528, 2023).
Chorea (1 paper, 2026). Chorea (Greek for 'dance') refers to widespread arrhythmic involuntary movements of a forcible, jerky and restless fashion. "De novo splice-donor-site variants at position +2 of intron 5 of SRRM4 (c.464+2T>C, c.464+2T>A) occurred in three unrelated patients with dystonia and chorea." (PMID 41958152, 2026).
COVID-19 (1 paper, 2023). A disease caused by infection with severe acute respiratory syndrome coronavirus 2. "Notably, we observed an overall higher association of protein coding transcripts, especially NAV3 and SRRM4, with the metabolic process and cytoskeleton organization associated pathways, suggesting a significant role of protein coding transcript isoforms in the COVID-19 pathogenesis." (PMID 37604131, 2023). "Most recently, both SRRM4 and NAV3 were reported to be upregulated in the COVID-19 patients’ nasopharyngeal tissue, indicating yet to be discovered specific functional roles, especially during infectious diseases, and awaits investigating the functional role in a focused way." (PMID 37604131, 2023).
diabetes (1 paper, 2021). "Besides Srrm4, the expression of two other neuron-specific splicing factors, Nova1 and Rbfox2, as well as the diabetes gene Glis3, which regulates splicing of Bim3, encoding an apoptosis protein, is lower in NZO than in B6-ob/ob islets." (PMID 34445304, 2021). "Expression of the neuronal splicing factor Srrm4 which mediates inclusion of microexons in mRNA transcripts was markedly lower in islets of diabetes-prone compared to diabetes-resistant mice, correlating with a preferential skipping of SRRM4 target exons." (PMID 34445304, 2021).
glioma (1 paper, 2020). A benign or malignant brain and spinal cord tumor that arises from glial cells (astrocytes, oligodendrocytes, ependymal cells). "We show here that ME-circEIF4G3 is controlled by SRRM4 and, given the down-regulation of SRRM4 in gliomas and association with poor survival outcomes, this may warrant further investigation of the role of this and other ME-circRNAs in gliomagenesis." (PMID 33207694, 2020). "Probing the GEPIA interactive web server, which incorporates over 18,000 matched tumor and normal samples from the TCGA and GTEx projects, we identified SRRM4 was significantly reduced in both GBM tumors and low-grade gliomas compared with healthy tissues." (PMID 33207694, 2020). "With respect to glioma, we identified a significant correlation (p < 0.0001) between low SRRM4 expression and poor survival in GBM and low-grade glioma across the Chinese Glioma Genome Atlas (CGGA), The Cancer Genome Atlas (TCGA) and Repository of Molecular Brain Neoplasia Data (Rembrandt) datasets." (PMID 33207694, 2020).
Human papillomavirus infection (1 paper, 2023). "SRRM4 is a known regulator of alternative splicing, while NAV3 is reported to be involved in multiple immune and infection-associated pathways such as FoxO signaling, T cell activation, and Human papillomavirus infection pathways." (PMID 37604131, 2023).
myelodysplastic neoplasms (1 paper, 2025). "SRRM4 KO UE7T-9 cells may be used to analyze hematological diseases such as myelodysplastic neoplasms." (PMID 41463596, 2025).
prostate adenocarcinoma (1 paper, 2023). "Further comparison of SRRM4 gene expression levels among NEPC, metastatic castration-resistant prostate cancer (CRPC), and primary prostate adenocarcinoma (PRAD) samples revealed that overexpression of SRRM4 is unique to NEPC, a finding that is consistent with a previous report." (PMID 37192158, 2023).
prostate tumors (1 paper, 2024). "Reduction of active REST by SRRM4-driven splicing has been shown to promote a NE phenotype in prostate tumors." (PMID 39080761, 2024).
Seizure (1 paper, 2024). A seizure is an intermittent abnormality of nervous system physiology characterized by a transient occurrence of signs and/or symptoms due to abnormal excessive or synchronous neuronal activity in the brain. "To further examine whether altered Cl- concentrations could cause this susceptibility to PTZ-induced seizure, we investigated the expression of Nkcc1 and Kcc2, the latter being transcriptionally regulated by Srrm4 through its downstream transcription factor REST." (PMID 38229888, 2024).
spinal muscular atrophy (1 paper, 2023). A motor neuron disease that affect the muscles, and characterized by muscle weakness and atrophy resulting from progressive degeneration and irreversible loss of the anterior horn cells in the spinal cord (i.e., lower motor neurons) and the brain stem nuclei. "Consequently, many AS-mediated diseases associated with nervous tissues are reported, including spinal muscular atrophy (SMA), resulting from Smn2 missplicing; autism spectral disorder (ASD), determined by a low expression of nSR100 (Srrm4) splicing factor; and many others." (PMID 36980872, 2023).
tumor (14 papers, 2017 to 2024). "Here, we report that the administration of SRRM4 ASO causes anti-tumor effects through the modification of alternative splicing from sREST to REST." (PMID 36650528, 2023). "SRRM4 expression is associated with tumor progression and development of resistance against clinical treatments." (PMID 36650528, 2023). "RE1-silencing transcription factor (REST) is a tumor suppressor, and its splicing isoform (sREST) is abnormally expressed by SRRM4 and causes carcinogenesis with neuroendocrine phenotype in SCLC." (PMID 36650528, 2023). "Furthermore, the abundance of microexon-containing circRNAs (ME-circRNAs) between tumor and normal tissues is correlated with the expression of a splicing associated factor, Serine/arginine repetitive matrix 4 (SRRM4)." (PMID 33207694, 2020). "Relative expression of SRRM4 was significantly reduced in tumours administered SRRM4_ASO plus L687 when compared with expression levels in tumours administered SRRM4_ASO with DMSO." (PMID 38621757, 2024). "Administration of SRRM4 ASO we previously developed effectively exhibited anti-tumor effects both in vitro and in vivo, while the detailed mechanism has not been well-studied." (PMID 36650528, 2023). "A recent study showed that InP/ZnS quantum dot treatment induced apoptosis, resulting in the downregulation of SRRM4 mRNA in HeLa cells, which prevented tumor growth." (PMID 36650528, 2023). "To address the anti-tumor effects by treatment with SRRM4 ASO, we assumed that the expression of the tumor suppressor REST through modification of alternative splicing reduced cell viability." (PMID 36650528, 2023). "Taken together, SRRM4 ASO exhibited anti-tumor effects by suppressing SRRM4 mRNA expression through the modification of alternative splicing from sREST to REST." (PMID 36650528, 2023). "Previous study showed that SRRM4 ASO effectively suppressed SRRM4 expression and induced anti-tumor effects against N417 cells." (PMID 36650528, 2023). "Here, we use public data from TCGA to analyze changes in SRRM4 expression and microexon inclusion between tumor and normal samples from 9 different tissues." (PMID 33621242, 2021). "Taken together, these results strongly suggest that the changes in SRRM4 expression observed between tumors and normal tissues are sufficient to provide a growth advantage to tumor cells with lower SRRM4 expression." (PMID 33621242, 2021). "Remarkably, SRRM4 is the most consistently silenced SF across all tumor types analyzed, implying a general advantage of microexon down-regulation in cancer independent of its tissue of origin." (PMID 33621242, 2021). "In fact, from a list of 202 known SFs (see “Definition of splicing factor list” in Methods), only SRRM4 had significantly decreased expression and increased promoter methylation across all tumor types." (PMID 33621242, 2021). "To further validate the finding that SRRM4 expression affects tumor growth, we performed a mouse xenograft experiment using the MDA-MB-231 cells with inducible SRRM4 expression (WT or DM)." (PMID 33621242, 2021). "Using publicly available, preprocessed RNA-seq data from TCGA, we first analyzed changes in SRRM4 expression between primary tumor (PT) and solid tissue normal (STN) samples." (PMID 33621242, 2021). "Using data from The Cancer Genome Atlas, this study shows that the splicing factor SRRM4 and its program of differentiation-promoting microexons are downregulated across tumor types with remarkable consistency, providing tumors with a proliferative advantage." (PMID 33621242, 2021). "Several recent studies have proposed various mechanisms of NEPC development, including modifications of the tumor microenvironment with epigenetic effects on cancer cells, as well as reports of molecular drivers such as SRRM4, FOXA1 and ONECUT2." (PMID 32252342, 2020). "This lower expression of SRRM4 in the core tumor compared with healthy tissue correlates well with the expression profiling from the publicly available IVYGap database." (PMID 33207694, 2020).